MGMT (O-6-methylguanine-DNA methyltransferase)
Diseases named in the same sentence as MGMT in open-access papers (continued):
Sharing a sentence is not in itself a finding about the gene and the disease.
glioma (continued). "Furthermore, some of CD133-positive glioma cultures highly expressed MGMT as well as target genes of the sonic hedgehog pathway." (PMID 17547775, 2007). "However, expression of O6-methylguanine-DNA methyltransferase (MGMT) renders glioma cells resistant to the treatment, indicating that identification of mechanisms underlying the gene regulation of MGMT is highly required." (PMID 17547775, 2007). "Interferon-beta has been reported to suppress MGMT in an experimental glioma model." (PMID 17683572, 2007). "Since MGMT seems to be regulated in several ways, it is possible that inhibitors of HDACs may be used for therapies for some glioma patients in combination with alkylating agents, such as temozolomide." (PMID 17547775, 2007). "Considering the attractive efficacy of temozolomide, one of the greatest challenges facing the field may be to identify therapeutic agents that suppress MGMT expression, as such drugs may sensitize resistant glioma cells to temozolomide." (PMID 17547775, 2007). "Moreover, MGMT also plays a role in regulating angiogenesis and might represent a potential predictive biomarker for glioma patients’ response to radiotherapy." (PMID 40881678, 2025). "Similarly, a higher percentage of MGMT methylation was related to a lower preoperative tumor volume, larger extent of resection, increased progression free survival and overall survival in glioma patients." (PMID 39796185, 2025). "Additionally, MGMT methylation is also associated with other molecular markers, such as IDH mutations, that could provide a more detailed understanding of glioma biology and its implications for different patient groups." (PMID 39834719, 2025). "Additionally, MGMT-methylated gliomas display lower ITSS grades than MGMT-unmethylated ones." (PMID 40052095, 2025). "Given that MGMT status is well established in adult glial tumor studies as a key predictor of temozolomide efficacy, it was hypothesized that patients undergoing concurrent temozolomide treatment might have harbored MGMT-methylated tumors." (PMID 40131412, 2025). "This subgroup analysis from an ongoing prospective study evaluates whether intraoperative in-vivo HSI enables rapid estimation of MGMT promoter methylation, potentially offering a practical, time-efficient tool for personalized decision-making in glioma surgery." (PMID 41247617, 2025). "The methylation status of the O6-methylguanine-DNA methyltransferase (MGMT) promoter is a key predictor of temozolomide chemosensitivity, whereas isocitrate dehydrogenase (IDH) mutations are strongly associated with molecular typing of gliomas and good prognosis." (PMID 40958862, 2025). "Indeed, a recent study of adult glioma highlights the prognostic and predictive impact of key molecular alterations, such as IDH mutation and MGMT promotor methylation status, suggesting using a molecular approach to guide therapy is clinically relevant and feasible." (PMID 40647406, 2025). "The reason for discrepancies between MGMT promoter methylation status and treatment response in certain patients may be due to inconsistencies between MGMT methylation and expression levels in glioma." (PMID 40427005, 2025). "Therefore, the objective of our investigation was to identify additional genetic alterations to the promoter’s methylation of the gene that codes for the MGMT protein, which will help explain the response to treatment with temozolomide in patients with high-grade gliomas." (PMID 39767683, 2024). "Additionally, the use of combination chemotherapy was limited to patients with MGMT promoter methylation, which is widely recognized as positive predictive marker due to the increased effectiveness of chemotherapy in glioma therapy and demanded as an inclusion criterion for the NOA09/CeTeG trial." (PMID 39518091, 2024). "Additionally, the proportion of non-enhancing lesions was associated with MGMT methylation in gliomas." (PMID 39594235, 2024).
glioma (continued). "Glioma patients with both the IDH1 mutation and MGMT methylation (3.0% of all patients) had the best overall survival, followed by patients with an IDH1 mutation and unmethylated MGMT promoter (1.0%), then by patients with MGMT promoter methylation and IDH1 wildtype (55.4%)." (PMID 39767640, 2024). "In cholangiocarcinoma, MGMT methylation increases the number of cells entering S-phase by inhibiting p21, p27, and Cyclin E expression, which could be a possible explanation for the observed effects in the glioma cell lines." (PMID 38357209, 2024). "Furthermore, Gupta and Salunke discussed molecular markers of glioma, underscoring the need to distinguish oligodendrogliomas based on MGMT promoter methylation status, which may offer insights into tumor behavior and response to therapy." (PMID 39055560, 2024). "Notably, glucocorticoids like dexamethasone, commonly used for high-grade glioma symptoms, may exacerbate tumor growth and resistance to temozolomide by upregulating MGMT expression." (PMID 39768232, 2024). "Methylation of the O-6-methylguanine-DNA methyltransferase (MGMT) promoter, the promoter for TERT (which encodes telomerase), isocitrate dehydrogenase 1 (IDH1), and codeletion of chromosome arms 1p and 19q (1p/19q codeletion) are important markers for the molecular classification of gliomas." (PMID 37149563, 2023). "We included both patients with astrocytomas grade 3 and 4 because the primary endpoint of this study was safety and tolerability; however, this certainly complicates interpretation of efficacy as IDH-mutant and/or MGMT promoter methylated gliomas may well respond to TMZ alone." (PMID 37554223, 2023). "Furthermore, the stratification analysis showed that high ISG20 expression may predict unfavorable OS in glioma patient subgroups with different age, sex, IDH mutation, 1p19q codeletion, and MGMT methylation (all P < 0.05)." (PMID 37380984, 2023). "In addition to histological characteristics, the WHO classification also emphasizes the importance of molecular markers for certain glioma types, such as IDH mutation status, 1p/19q codeletion, and MGMT promoter methylation, which can have prognostic and predictive implications." (PMID 37444408, 2023). "The central hypothesis was that glioma samples with low VAF are at risk of false negative MGMT assay results due to dilution of tumor methylation signals by non-neoplastic cells." (PMID 37919784, 2023). "To further explore the expression pattern of ISG20 in glioma, we analyzed the expression of ISG20 in patient subgroups with disparate clinical characteristics, including age, gender, IDH mutation, 1p19q co-deletion, MGMT methylation, WHO grade, histology, and primary therapy outcome." (PMID 37380984, 2023). "Likewise, a patient taking TMZ may continue therapy even if radiology suggests tumor progression, so long as the glioma has MGMT promoter methylation." (PMID 37919784, 2023). "Moreover, high-risk scores were also associated with unmethylated MGMT promoter, 1p19q non-code, recurrent glioma, and IDH wild-type genotype in the training set." (PMID 37004060, 2023). "Therefore, this study aimed to firstly investigate the association between WHO grade and the ADC values of gliomas, secondly evaluate the predictive capability of ADC in genetic markers (e.g., IDH, MGMT, and TERT) in gliomas, thirdly confirm the parameters that affect the ADC values." (PMID 36471242, 2022). "Significantly, the hypermethylation of the MGMT promoter and low MGMT expression may play a crucial role in glioma occurrence and progression and were found to be responsible for the favorable prognosis of LGGs and GBMs treated with TMZ with or without additional radiotherapy." (PMID 36361838, 2022). "In addition, multiple Cox regression revealed grade, IDH mutations, 1p/19q codeletions, promoter methylation of MGMT, and PLK1 mRNA levels might be independent predictors of prognosis of glioma patients." (PMID 36618405, 2022).
glioma (continued). "Besides, high DNAJC10 expression was also significantly associated with MGMT unmethylated status (Wilcoxon rank-sum test), IDH wild status (Wilcoxon rank-sum test) and 1p/19q non-codeletion status (Wilcoxon rank-sum test) in gliomas." (PMID 34988580, 2022). "The finding that low-grade gliomas with an IDH mutation frequently have a methylated MGMT promoter could be extrapolated to high-grade gliomas, which might potentially explain the nonsignificant trend in this study." (PMID 35804921, 2022). "However, due to MGMT had potential to repair the damage DNA, 55% glioma had resistance to TMZ." (PMID 36118887, 2022). "In gliomas, the TETs may play a particularly important role as DNA hypermethylation is a good prognostic indicator, and suppression of DNA repair via methylation of the O-6-methylguanine-DNA methyltransferase (MGMT) promoter predicts response to temozolomide." (PMID 35419292, 2022). "However, O6-methylguanine-DNA methyltransferase (MGMT) inhibits the anti-glioma activity of TMZ." (PMID 36059989, 2022). "Interestingly, MGMT promoter methylation is rarely observed in H3K27M-altered gliomas." (PMID 36147920, 2022). "Interestingly it has been previously shown that VPA downregulates MGMT expression in glioma cells." (PMID 36465345, 2022). "However, as for the methylation of MGMT promoter, risk score did not share the consistent trend in the TCGA and CCGA dataset, where risk score was significantly elevated in MGMT unmethylated glioma in the TCGA dataset (p<0.05) but not in CCGA dataset (p>0.05)." (PMID 34659218, 2021). "Hypermethylation of the MGMT promoter region results in gene silencing, accompanied by decreased DNA repair, an effect that is seen in various tumors, including lung carcinoma, head and neck carcinomas, lymphoma, colorectal carcinoma, melanoma, as well as glioma and particularly oligodendrogliomas." (PMID 33917711, 2021). "Additionally, the MGMT promoter methylation varies widely in gliomas in the range of 35% to 84%." (PMID 33801310, 2021). "Therefore, MGMT expression or activity in glioma cells may directly affect the resistance of cells to TMZ." (PMID 33460245, 2021). "Secondly, MGMT promoter methylation status was a significant prognostic factor; however, its data were absent because most of the patients are not tested in our study, leading to the role of MGMT promoter status in our inability to assess short-term glioma recurrence." (PMID 34778058, 2021). "In addition, the difference remained significant in eight out of these nine subgroups and marginally significant in grade IV glioma after taking into account age, gender, histology, IDH mutation status, MGMT methylation status, and co-deletion of 1p and 19q (Log-rank test, P < 0.05)." (PMID 34722280, 2021). "Moreover, by analyzing the clinical characteristics of patients with glioma, we found that the risk score was positively correlated with malignancy and negatively correlated with protective factors (e.g., IDH mutation, 1p19q codel, and MGMT methylation)." (PMID 34123852, 2021). "On the other hand, in glioma patients undergoing the alkylating agent temozolomide treatment, low MGMT expression was found to improve patient survival and treatment response, which may be due to the incomplete repair of temozolomide induced DNA alkylation damage in glioma cells." (PMID 34544433, 2021). "Synergistically adding the epigenetic information to routine examinations, including MRI imaging, MGMT promoter methylation, IDH mutation, loss of 1p/19q, BRAF fusion, and CpG island methylator phenotype (CIMP), are of crucial and predictive significance for glioma diagnosis." (PMID 34887381, 2021). "NF‐κB and MGMT may serve as valuable therapeutic targets in RIP2‐positive gliomas." (PMID 33460245, 2021). "Therefore, it is worthwhile to evaluate the role of the eQTLs of MGMT in glioma development." (PMID 34544433, 2021).
glioma (continued). "As we know, the MGMT promoter methylated status has a confirmed association with TMZ therapy in GBMs; thus, we imply that ANXA1 not only functions as an important factor of the post-surgery recurrence of glioma but also results in the resistance of TMZ chemotherapy." (PMID 34912807, 2021). "Therefore, we detected the effect of SD‐36 on MGMT expression in glioma." (PMID 34291563, 2021). "Glioma patients may not respond to chemotherapy of alkylating agents due to the alkylator resistance caused by pivotal DNA repair enzyme such as O6-methylguanine-DNA methyltransferase (MGMT)." (PMID 34422648, 2021). "Interestingly, we found that the nomogram including preoperative PNI, age, extent of resection, number of gliomas, and MGMT methylation status could predict the prognosis of patients with grade IV glioma well." (PMID 35096561, 2021). "Similarly, MGMT methylated glioma samples were enriched in cluster 2 (p < 0.05)." (PMID 34211979, 2021). "High correlations between the risk score and unmethylated MGMT promoter indicate that patients with high risk scores may display an unfavorable response to temozolomide (TMZ), the most frequently used chemotherapy drug for glioma." (PMID 33459509, 2021). "MGMT expression levels in gliomas may influence responses to alkylating agents." (PMID 34638714, 2021). "The biological mechanism of interaction between TERT promoter mutation and MGMT methylation that may influence sensitivity to TMZ treatment of gliomas has not yet clearly defined." (PMID 32957941, 2020). "MGMT promotor methylation may predict response to chemotherapy in glioma WHO grade III and IV24,25." (PMID 33184319, 2020). "Furthermore, there were also profound differences in the steady-state levels of several proteins implicated as therapeutic targets in GB such as glioma promoting factor TGFβ, TMZ-resistance factor MGMT, stemness marker CD133/Prominin-1 or the marker of Proneural subtype PDFGRα." (PMID 32102350, 2020). "Gliomas with MGMT fusions or hypomethylated MGMT promoter had significantly higher MGMT expression, while the DNA hypermutated patients showed the lowest MGMT expression, even lower than the MGMT-methylated tumors (P-values calculated by Wilcoxon rank-sum test)." (PMID 32753598, 2020). "From our results, the OS of gliomas can be further stratified into four distinct survival subgroups with ascending survival time as follow: TERT-mut/MGMT-unmeth << TERT-wt/MGMT-unmeth << TERT-wt/MGMT-meth << TERT-mut/MGMT-meth which is consistent with previous reports." (PMID 32957941, 2020). "Furthermore, it was seen in our study that different combinations of IDH1/2 mutational statuses (irrespective of either wild or mutated) and MGMT methylation showed a better prognosis for survival in glioma patients." (PMID 33552543, 2020). "Even with these limitations, our study indicates a clue to approach the in vitro models of glioma with the expression pattern of driver genes (including the MGMT promoter methylation status): not all cells in a glioma TS are directly associated with the driver-associated genes." (PMID 33317554, 2020). "The impact of glioma reclassification based on molecular profiling has subsequently been studied and 3 genetic alterations have been extensively validated: O-6-methylguanine-DNA methyltransferase (MGMT), isocitrate dehydrogenase (IDH), and 1p/19q co-deletion status." (PMID 32705083, 2020). "Due to the histopathological heterogeneity of gliomas, RNA-seq data of glioma samples from three independent databases were analyzed according to WHO guidelines, and the analysis included IDH mutation status, 1p/19q co-deletion status, and MGMT promoter status." (PMID 33329553, 2020). "In our cohort, the MGMT promoter methylated gliomas (n = 10) had a higher overall mean APTw signal intensity of 2.38% compared to 1.92% for non-methylated gliomas (n = 3), albeit, the differences in levels of APTw signals could not be statistically analysed due to insufficient number of patients." (PMID 33373375, 2020).
glioma (continued). "Moreover, MGMT promoter methylation was only identified in H3-wildtype gliomas." (PMID 32228694, 2020). "Therefore, monitoring anti‐MGMT‐02 peptides autoantibody could be valuable for the recurrence of glioma." (PMID 31210005, 2019). "We assessed the SWI signals of patients with gliomas to determine ITSS and pathological grades as well as expression levels of molecular markers, to assess correlations between ITSS grades and pathological grades, IDH1 mutation status, MGMT promoter methylation status, and 1p19q deletion status." (PMID 31745161, 2019). "Importantly, MGMT promoter hypermethylation has been identified in approximately 40% of gliomas." (PMID 31652645, 2019). "Moreover, combined treatments of PP7 with TMZ resulted in more effective cytotoxicity and decreased MGMT expression, which can be foreseen as a strategy to attenuate the ability of glioma cells to repair the TMZ-induced DNA methylation and therefore reduce the resistance of TMZ (right)." (PMID 31814867, 2019). "In contrast, MGMT promoter methylation has been shown to be a strong biomarker of prognosis and a predictor of response to chemotherapy, reinforcing the idea that this biomarker should be include in glioma classification, resulting in a new molecular subgroup within the GBM IDH-wildtype." (PMID 31623593, 2019). "Moreover, given that glioma sub-types are stratified according to the MGMT promoter methylation status, wherein telomerase reverse transcriptase (TERT) status showed distinct tumor characteristics and OS outcomes, we investigated the prognostic value of risk score in these populations." (PMID 31921684, 2019). "Therefore, we suggest MGMT promoter methylation should be added to glioma classification." (PMID 31623593, 2019). "Today, the IDH gene status or the methylation of the promoter of the MGMT gene have a prognostic and predictive role, and should be considered possible confounders in statistical analyses when trying to determine the importance of a protein marker in the biology of a glial tumor." (PMID 31357616, 2019). "Several studies have revealed that chemotherapy may enhance MGMT expression in gliomas." (PMID 32010632, 2019). "Finally, in addition to 18F-FDG-PET data, multimodality imaging data (e.g., data from MRI and PET with alternative tracers) may be further integrated into the radiomics model for predicting the MGMT promoter methylation status in glioma." (PMID 31426864, 2019). "Further, on methodological aspects more refined MGMT protein detection by IHC or any other method or a tool may help to improve the results in protein validation for effective interpretation for TMZ therapy response in glioma." (PMID 29712977, 2018). "Studies reported that TOPK could activate NF-κB in HeLa cells and reduction of NF-κB activity could reverse TMZ resistance by MGMT expression in glioma cells, which implied that TOPK could promote MGMT expression through activation of NF-κB to lead to TMZ resistance." (PMID 29487691, 2018). "In Kaplan-Meier survival analyses worse overall survival was observed in patients with increasing age, WHO grade IV glioma, lower Karnofsky Performance Score, incomplete resection or biopsy only, unmethylated MGMT promoter status, absence of IDH mutation and absence of combined radiochemotherapy." (PMID 30507932, 2018). "Moreover, combined analysis of Alu and MGMT showed higher sensitivity for glioma diagnosis." (PMID 29100349, 2017). "Therefore, both serum Alu and MGMT methylation level could be useful tools to predict the prognosis of glioma patients." (PMID 29100349, 2017). "Therefore, both serum Alu and MGMT methylation levels may represent a novel prognostic factor for glioma patients." (PMID 29100349, 2017). "IDH mutations in low-grade gliomas have a significantly positive effect on overall survival (hazard ratio, 0.64) with TMZ treatment, independent of histologic phenotype, and usually predict the presence of MGMT promoter methylation in 84% of IDH-mutant low-grade tumors." (PMID 28346397, 2017).